RAC1 (Rac family small GTPase 1)
Diseases named in the same sentence as RAC1 in open-access papers (continued):
Sharing a sentence is not in itself a finding about the gene and the disease.
infection (continued). "The infection of EHV-1 was significantly reduced in cells treated with Rac1 (~60%) and Cdc42 inhibitors (~40%)." (PMID 32645930, 2020). "Infection by E. chaffeensis is accompanied by increase in activation of the Wnt signaling intermediates Rac1 and Disheveled." (PMID 31736969, 2019). "Wnt5a-RAC1-Disheveled mediated cytoskeletal actin rearrangement facilitates autophagy and containment of infection." (PMID 31736969, 2019). "Overall, our study unveils the prevalence of a Wnt5A—Rac1—Disheveled-mediated actin-associated autophagy circuit as an important component of innate immunity in host macrophages that may turn out crucial for restricting infection by leading bacterial pathogens." (PMID 29686674, 2018). "Infection with both, RAC1 (WT) and RAC 1(CA) decreased α-SYN expression level (Online Resource 5b) and aggregation, as shown by Thioflavin S (ThyoS) dye, which specifically stains cross-beta sheet fibrils, such those forming amyloid aggregates." (PMID 29429047, 2018). "Only inhibition of Rac1 (by NSC23766) hampered viral replication showing significantly stronger effect when present prior to infection (7.9% ± 9.3 of control) than after (51.9% ± 3.6 of control) implying its involvement in entry process." (PMID 29970183, 2018). "The role of both cellular factors during ASFV infection was also demonstrated by transfecting cells with dominant-negatives for both Pak-1 (pEGFP-Pak-1-AID) and Rac-1 (pcDNA-Rac-1 N17), which inhibited the infection and the synthesis of ASFV early proteins." (PMID 29117102, 2017). "The results also showed P. gingivalis infection can temporally modulate NOX2 pathway by reorganizing the localization and activation of cytosolic molecules (p47phox, p67phox, and Rac1) during 24 h of infection." (PMID 28725637, 2017). "The data suggest that Kif15 recruits EspW to the site of bacterial attachment, which in turn activates Rac1, resulting in modifications of the actin cytoskeleton that are essential to maintain cell shape during infection." (PMID 28630074, 2017). "Knock-down experiments using specific siRNAs indictated that Rho GTPase Rac1 regulates EV1 infection and is possibly the upstream regulator of PAK1." (PMID 28430160, 2017). "Micrographs of this localization shift in Rac1, provides visual support of the changes which occur following ATP treatment and the infection." (PMID 28725637, 2017). "The endocytic process (membrane ruffling) mediated by beta integrins (e.g., CDC42 and RAC1) was mildly increased at T3h, but inhibited T24h after infection." (PMID 28491823, 2017). "Actin foci are generated late in infection concomitantly with alphavirus envelope (E2) expression and are dependent on the activities of Rac1 and Arp3." (PMID 27031835, 2016). "At 30 min post-infection (mpi), the level of activated Rac1 the same or lower than at the 10 min time point." (PMID 27861142, 2016). "Rac1 activities decreased during the early phase and gradually increased by the late phase of infection." (PMID 27056258, 2016). "Rac1 and NAPDH oxidase (Nox1) are important contributors of ROS generation following infection and associated with gastrointestinal epithelial injury." (PMID 26761793, 2016). "After specific inhibition on actin, Na+/H+ exchanger, receptor tyrosine kinase, Rac1, Pak1, myosin II, and protein kinase C, the entry and infection of FMDV significantly decreased." (PMID 26757826, 2016). "We revealed an actin-remodeling pathway involving Rac1, PIP5K1- α, and Arp3, as essential for infection by pathogenic alphaviruses." (PMID 27031835, 2016). "Although activation of Rac1 by H. pylori has been previously reported, here we expand this finding by showing that Rac1 is involved in the production of ROS by gastric epithelial cells following infection with H. pylori." (PMID 26761793, 2016). "This interaction inhibits Rac1 activation and Nox1 expression, decreasing ROS generation that results from infection." (PMID 26761793, 2016).
infection (continued). "As a positive control for infection inhibition, HeLa cells were pretreated with increasing concentrations of Rac1 or Arp3 inhibitors 1 h before addition of virus." (PMID 27031835, 2016). "The inhibitory effects of both Rac1 mutant variants on alphavirus infection likely indicate that the role of Rac1 during infection requires completion of the GTP-GDP-exchange/GTP-hydrolysis cycle." (PMID 27031835, 2016). "For example, Salmonella’s SopE and SptP toxins act antagonistically to activate and inactivate Rho-family GTPases CDC42 and Rac1 at different times of infection via a combination of differential activity and temporal stability." (PMID 25774515, 2015). "Expression of EGFP and Rac1 in BLA was detected 2 weeks after infection to verify the effect of viral expression." (PMID 26582975, 2015). "The results indicated that the Rac1 protein was linearly upregulated at 3, 6, and 9 hours after infection, followed by significant downregulation at 12 hours after infection." (PMID 25243137, 2014). "In case of dengue viruses, Rac1 activity seems to impair the entry process and is downregulated during the early stages of the infection." (PMID 24523909, 2014). "We had shown before that Rac1 is involved in the onset of the type-I interferon response upon IV infections and that expression of dominant-negative mutants results in increased virus titers." (PMID 24523909, 2014). "The over-expression of a dominant negative mutant form of Rac1 led to reduced interferon-β production, which is the main response of the innate immune system to IV infections." (PMID 24523909, 2014). "This seemed to be contradictory to our former study, which identified Rac1 as positive regulator of interferon β expression after IV infections." (PMID 24523909, 2014). "The infection rates of RhoA and Rac1 silenced cells were about 65% of that of the mock cells, while the infection rate of RhoA and Rac2 double-silenced cells was about 50% of that of the mock cells." (PMID 23721065, 2013). "The results obtained showed a dramatic reduction of active Rac1 levels 15 min post infection and undetectable levels 1 h later in macrophages infected with wild type Mtb." (PMID 23874203, 2013). "To delineate the hierarchy of the PorBIA/SREC-I invasion signaling pathway, we applied inhibitors of the identified components and assayed the activation of PI3K via Akt phosphorylation as well as Rac1 upon infection with N927." (PMID 23717204, 2013). "Monocytes were pretreated with nystatin (disrupts caveolar structure and function), genistein (disrupts caveolae-mediated endocytosis), Rac1 inhibitor (Rho GTPase inhibitor) and dynasore (dynamin inhibitor) prior to BADrUL131 infection." (PMID 23853586, 2013). "Prominent members are the GTP-binding proteins RhoA, Cdc42 and Rac1, which act as guanine nucleotide-regulated switches to induce various responses during the infection process." (PMID 22204307, 2011). "In Salmonella-infected HeLa cells, activation of Rac1 started within 30 min after infection and increased over 3 h of infection." (PMID 20111723, 2010). "To gain insights into the mechanism by which activity of Rac1 GTPase is modulated in DV2 infection, we analyzed the distributions of Rac1 and viral envelope proteins first." (PMID 20824170, 2010). "Given that CT166-mut binds Rac1 and temporarily prevents its covalent modification, this observation indicates that C. trachomatis D-induced actin re-organization includes Rac1 during infection." (PMID 20360858, 2010). "It is noteworthy that Rac1 activity is up-regulated in the late phase of DV2 infection, and dominant negative Rac1 inhibited DV2 production and release." (PMID 20824170, 2010). "The active form of Rac1 was significantly decreased when cells were treated overnight with Sb before ST infection." (PMID 20111723, 2010). "Cell rounding induced by high MOI infection with C. trachomatis D was reduced in cells expressing CT166-mut or Rac1-G12V, and in CNF1 treated cells." (PMID 20360858, 2010).
infection (continued). "In this study, we show that the Rac1 GTPase plays a critical role in the formation of conidia and appressoria for infection of rice." (PMID 19008945, 2008). "Nevertheless, we measured the fraction of activated Rac1 and Cdc42 at various times after infection with PAK, PAKΔSΔT, PAKΔS or PAKΔT." (PMID 18369477, 2008). "Furthermore, infection with these recombinants also suppressed the expression of Rac1, a Rho-small family GTPase that promotes actin polymerization assembly during filamentation." (PMID 39949767, 2025). "To test whether inhibition of RhoGTPases could affect HIV infection in U937 control or Myo9b-silenced cells, we treated these U937 with inhibitors to RhoA, B and C (C3) or to Rac1 (NSC23766) for 4 h before infection with VSV-G-pseudotyped HIV-1." (PMID 40167026, 2025). "We expressed Rac1 mutant forms prior to infection and obtained comparable results." (PMID 38809020, 2024). "Notably, an increase in GTP-bound (active) forms of RhoA, Rac1 and Cdc42 was observed in WT cells after 1 h of infection; however, such activation was largely prevented in Egr-1-knockout cells." (PMID 38233877, 2024). "Therefore, we concluded that SIRT7, in its role regulatingcytoskeletal remodeling through RAC1, is critical for host responses duringMtb infection and proposes a potential target fortuberculosis treatment." (PMID 39287444, 2024). "We then examined involvement of Rac1 in formation of NOX2 complexes to defend against infection." (PMID 39043696, 2024). "Additionally, RABV induces biphasic dynamics of epidermal growth factor receptor (EGFR)-phosphatidylinositide-3 kinase (PI3K)-Rac1 signaling at early infection and impedes Rac1-p21-activated kinase 1 (Pak1) transduction later." (PMID 38809020, 2024). "Similarly, in human macrophages, infection with L. amazonensis, L. braziliensis or L. infantum resulted in reduced Rac1, Cdc42, and RhoA expression in a 3D environment compared to uninfected controls." (PMID 37576604, 2023). "However, we also identified reduced expression of Rac1 and Cdc42 following infection by all three Leishmania spp." (PMID 37576604, 2023). "How does PAR2 induce Rac1 activity in macrophages upon PA infection?" (PMID 36204227, 2022). "Interestingly, during C. jejuni invasion, LC3 was recruited to bacterial entry site depending on Rac1 GTPase activation just at the early step of the infection." (PMID 35310852, 2022). "The addition of bacterial-cultured supernatants, which removed bacterial cells, also increased LC3 and the infection of living C. jejuni, this data suggested that this pathogen-induced autophagy occurs in the earliest step of the infection before Rac1 signaling activation." (PMID 35310852, 2022). "Many viruses employ Rac1 protein to regulate their infection." (PMID 34730435, 2021). "Control cells expressing Rac1 V12 had numbers of intracellular bacteria that were not statistically different than the numbers from APE1-deficient cells after 1 h infection." (PMID 33603730, 2020). "In addition to evidence of proximity in the cells following infection with S. Typhimurium and AIEC, APE1 was able to regulate levels of active Rac1 after infection." (PMID 33603730, 2020). "Furthermore, infection with WR Vaccinia virus is highly dependent on Rac1, whereas infection with IHD-J is highly dependent on Cdc42, highlighting the existence of different pathways of macropinocytosis that can be exploited by viruses." (PMID 32756454, 2020). "Activation of Rac1 was augmented following infection but negatively regulated by APE1." (PMID 33603730, 2020). "In this study, we show that EHV-1 activates the small GTPases Rac1 and Cdc42 during infection." (PMID 32645930, 2020). "As treatment with Vi inhibited invasion of epithelial cells with Salmonella, we analyzed whether incubation with this polysaccharide might alter the ability of these cells to activate Rac-1 and Cdc42 during infection with S. Typhimurium." (PMID 31134159, 2019).
infection (continued). "Additionally, Rho GTPases, such as Cdc42, Rac1 and Rac2, regulate phagocytosis by altering hemocyte cell shape after infection." (PMID 30518379, 2018). "Two of the four modules positively correlated with infection status were enriched for a number of innate and adaptive immune response terms, including both T cell and mast cell processes (e.g. rac1, rc3h1)." (PMID 30285628, 2018). "Infection of Swiss cells with an EHEC espW deletion mutant induces a cell shrinkage phenotype that could be rescued by Rac1 activation via expression of the bacterial guanine nucleotide exchange factor, EspT." (PMID 28630074, 2017). "Furthermore, we demonstrate that P. gingivalis infection successfully rearranges and shifts the presence of active or inactive components (p47phox, p67phox, and Rac1) of the NOX2 complex at various time points of infection." (PMID 28725637, 2017). "In addition, analysis of the localization of interacting subunits Rac1 and p67phox during ATP treatment and P. gingivalis infection reveals similar trends of an increase at 3 h with infection only and decrease at 24 h of P. gingivalis infection." (PMID 28725637, 2017). "Interestingly, we found that EPEC and EHEC strains expressing EspM also express either EspT or EspW, suggesting that activation of RhoA and Rac1 need to be coordinated during infection." (PMID 28630074, 2017). "Because our data suggested that the timing of the effects of Rac1 and Arp3 and the formation of actin foci take place late in infection, we speculated that Rac1 and Arp3 proteins might play a role in this alphavirus-induced actin remodeling." (PMID 27031835, 2016). "In order to examine whether B. bronchiseptica-induced membrane ruffle depends on Rac1 activities, we performed an infection assay of L2 cells treated with NSC23766, a Rac1 inhibitor." (PMID 26828590, 2016). "However, our time-of-addition experiments suggest that Rac1 and Arp3 play a role later in infection." (PMID 27031835, 2016). "To test the hypothesis that migration inhibition by LAI-1 or L. pneumophila converges on common host factors, we depleted the small GTPases Cdc42 or Rac1 in A549 cells prior to an infection with wild-type or ΔicmT mutant L. pneumophila." (PMID 26633832, 2015). "Furthermore, vesicular trafficking of entering viral particles is influenced by Rac1 during infections with adenovirus, african swine fever virus, and Ebola virus." (PMID 24523909, 2014). "In case of IV infections, we have shown that Rac1 is activated upon infection." (PMID 24523909, 2014). "Initially we elucidated whether the specific inhibitor NSC23766, which prevents the interaction of Rac1 with its GEFs Tiam1 and Trio, exerts an antiviral effect against IV infection in cultured cells." (PMID 24523909, 2014). "Binding of HIV-1 envelope glycoprotein to the CD4 receptor and CCR5 or CXCR4 co-receptors induces a signaling cascade that results in Rac1 activation and actin cytoskeletal reorganizations, changes that are required for efficient viral-mediated membrane fusion and infection." (PMID 24571616, 2014). "Our analysis demonstrated that absence of YopE caused no or only a small increase in Rac1/RhoA activation and Yop translocation during infection of murine macrophages with Y. pseudotuberculosis YPIII with or without treatment with CNFY." (PMID 24244167, 2013). "In our research, we are not clear about the upstream cell signaling component of the Rho and Rac GTPases involved in T. gondii infection, but we have witnessed the activation of RhoA and Rac1 of host cells and the reorganization of the cytoskeleton for PV formation during the infection of T. gondii." (PMID 23721065, 2013). "Some effector proteins, in particular YopE, were shown to inhibit Yop delivery by inactivation of RhoA and Rac1 most likely as part of an intra-cellular control mechanism which measures and adapts the amount of protein translocated by Yersinia during infection." (PMID 24244167, 2013).
infection (continued). "Moreover, the Rac1 inhibitor also reduced the IL-1β production in C. pneumoniae–infected cells when added 2.5 hrs post infection." (PMID 22276187, 2012). "Furthermore, Rac1 activation, which triggers microtubule acetylation and stabilization, is crucial for infection at early time points." (PMID 23133661, 2012). "A first hint pointing in this direction has been given by a recent study showing that EBOV entry leads to the activation of the PI3K/Akt signaling pathway very early in infection, resulting in the activation of Rac1, a regulator of endocytosis and vesicular trafficking." (PMID 21927676, 2011). "Thus, it has been shown for influenza virus that transient PI3K activation during entry leads to the activation of Rac1, while late in infection, PI3K activation prevents the induction of premature apoptosis." (PMID 21927676, 2011). "DV2 entry induced reduction of Rac1 activity within 1 hour post infection." (PMID 20824170, 2010). "Taken together, these results suggested multiple roles of Rac1 GTPase in DV2 infection." (PMID 20824170, 2010). "Additionally, exposure to Sb before the infection modulates activation of Rac1, MAPK and NF-κB during infection." (PMID 20111723, 2010). "Furthermore, using the CRIB domains of PAK and WASP that bind activated Rac-1 and Cdc42, respectively, we demonstrate that EspT activates both Rac-1 and Cdc42 during infection of Swiss 3T3 cells." (PMID 19016787, 2009). "This ‘feed-forward’ amplification and evolved effector interdependency may allow the Cdc42/Rac1-dependent pathway to dominate during WT infection." (PMID 18389058, 2008). "Interestingly, treatment with this compound also reduces F-actin polymerization, suggesting that Rac1 activation may entail F-actin cytoskeleton modulation, as previously reported in infection by many other intracellular pathogens." (PMID 35889089, 2022). "In the later stage of infection, focal adhesion pathway was associated with ECM receptor interaction pathway through SPP1, col6a2, COL3A1 and VTN proteins, while focal adhesion pathway linked with leukocyte transendothelial migration pathway by RAC1 and LOC733637." (PMID 32632500, 2020). "Infection with S. Typhimurium resulted in further enrichment of prohibitin and Rac1 in fraction 6 indicating that this fraction might represent a domain that serves as the site for initiation of cellular events required for bacterial invasion and induction of inflammatory responses." (PMID 31134159, 2019). "Finally, we confirmed the importance of Rac1:PIP5K1-α complex formation to infection with CHIKV." (PMID 27031835, 2016). "Wild-type RhoA or Rac1 overexpressed cells had almost the same infection rates by T. gondii as the mock-treated cells, while RhoA-N19 or Rac1-N17 transfected cells and RhoA, Rac1 or RhoA + Rac1 siRNA-treated cells showed significantly diminished infection rates compared to mock cells." (PMID 23721065, 2013). "Although these protein analyses and our studies were performed at different infection times, GTPases family members such as CDC42, RAC1 and RHO were found dysregulated suggesting them as essential players in the infection." (PMID 40396886, 2025). "Activation of RhoA and Rac1, for example, modulates ACE2 expression, potentially increasing infection rates." (PMID 39653747, 2024). "Immunoprecipitation (IP) assays showed that infection by the EF, EF::RDTND-RIDC/A, EF::RDTNDE/Q-RIDC/A, or EF::RDTND4mt-RIDC/A led to a marked increase in the NOX2/gp91phox interaction with Rac1, p47phox, and p67phox in macrophages." (PMID 39043696, 2024). "In contrast, infection of AGS cells transfected with siRNAs, interfering with cortactin, Vav2 or Rac1 expression exhibited strongly reduced wound healing activities." (PMID 34439396, 2021). "Here, we show that, late during infection, SV40 activates a signaling cascade in permissive monkey CV-1 cells involving Ras, Rac1, MKK4, and JNK to stimulate SV40-specific cytoplasmic vacuolization and subsequent cell lysis and virus release." (PMID 33028008, 2020).